HDAC4 (histone deacetylase 4)
Diseases named in the same sentence as HDAC4 in open-access papers (continued):
Sharing a sentence is not in itself a finding about the gene and the disease.
head and neck cancer (5 papers, 2018 to 2023). A primary or metastatic malignant neoplasm affecting the head and neck. "We found that HDAC4 overexpression by lentiviral transduction increased proliferation of the head and neck cancer cell line Cal27 significantly compared to vector control cells." (PMID 36982651, 2023). "To investigate the role of class IIa HDACs in head and neck cancer and possible implications for chemoresistance, we generated stable HDAC4 and HDAC5 overexpression clones by lentiviral transduction." (PMID 36982651, 2023). "HDAC inhibitors have been used to target and degrade HDAC4 and disrupt cancer stem cells in head and neck cancers." (PMID 36362284, 2022). "Additional support for a beneficial effect of class IIa HDACi in the management of HDAC4-expressing head and neck cancer cells comes from our gene expression study (RNAseq) in control and HDAC4-overexpressing Cal27 cells without and with 5 μM CHDI0039 treatment." (PMID 36982651, 2023). "Therefore, we initially anticipated that the combination of a class IIa selective HDACi with cisplatin would be beneficial in the treatment of head and neck cancer cells with high HDAC4 expression." (PMID 36982651, 2023). "Taken together, neither HDAC4 nor HDAC5 expression status nor class IIa HDAC inhibition had a notable influence on cisplatin sensitivity in the head and neck cancer cell lines Cal27 and Cal27CisR (shift factors < 2) in contrast to results with vorinostat." (PMID 36982651, 2023).
leiomyosarcoma (5 papers, 2021 to 2024). An uncommon, aggressive malignant smooth muscle neoplasm, usually occurring in post-menopausal women. "As a second model of cellular senescence, we chose low-grade leiomyosarcoma cells SK-LMS-1 that undergo senescence after HDAC4 knock-out." (PMID 38383514, 2024). "Further, eliminating HDAC4 in leiomyosarcomas, cancers known for high expression of HDAC4, led to senescence, arrested proliferation, and enriched SASP factors." (PMID 35203320, 2022). "HDAC4 is upregulated in leiomyosarcoma, and LMK235, a specific HDAC4 inhibitor, dose-dependently suppressed MKK7 transcription and JNK/c-Jun activity in early brain injury following subarachnoid hemorrhage and impaired neuronal apoptosis." (PMID 35008848, 2021). "We initially selected leiomyosarcoma SK-LMS-1 cells, deleted for HDAC4 using CRISPR/Cas9 and re-expressing a 4-hydroxytamoxifen (4OHT)-inducible PAM mutant version of HDAC4 (HDAC4−/−/HDAC4PAM-ER) as a model of inducible senescence." (PMID 38874468, 2024). "HDAC4 and HDAC9 are upregulated in leiomyosarcoma, and HDAC2 is activated in liposarcomas." (PMID 35008848, 2021).
nasopharyngeal carcinoma (5 papers, 2021 to 2024). A carcinoma arising from the nasopharyngeal epithelium. "HDAC4 has previously been associated with advanced tumor stage in esophageal and nasopharyngeal carcinoma." (PMID 36901692, 2023). "However, the role of HDAC4 dysregulation and mechanisms underlying tumor growth and metastasis in nasopharyngeal carcinoma (NPC) remain elusive." (PMID 33542203, 2021). "HDAC4 was overexpressed in nasopharyngeal carcinoma (NPC) cells and promoted their proliferation and metastasis by upregulating TYK2-STAT1 phosphorylation through HDAC4/LHPP signal axis." (PMID 38702756, 2024). "Targeted inhibition of HDAC4 has been shown to inhibit the growth and metastasis of HCC, and HDAC4 can promote the proliferation, migration and invasion of nasopharyngeal carcinoma cells in vitro, as well as tumor growth and lung metastasis in vivo." (PMID 35355509, 2022).
sarcopenia (5 papers, 2014 to 2025). Progressive decline in muscle mass due to aging which results in decreased functional capacity of muscles. "Likewise, a recent study published by our group showed how a mixture between algae and EVOO oils also prevented sarcopenia in aged rats, an effect that was associated with a decrease in the gene expression of both HDAC-4 and myogenin in the gastrocnemius muscle." (PMID 34067004, 2021). "Another factor that seems to play a major role in sarcopenia is HDAC-4, a class IIa HDAC that deacetylates myosin heavy chains, PGC-1α, and Hsc7 to control muscle homeostasis." (PMID 34067004, 2021). "Moreover, these same authors also demonstrated the involvement of histone deacetylase 4 (HDAC-4) in sarcopenia development." (PMID 36079827, 2022). "Decline in human muscle mass and strength (sarcopenia) is a hallmark of the aging process; whether methylation changes in genes such as LMNA, TNNT3, ELN and HDAC4 are a cause or consequence of this process merits investigation." (PMID 24112369, 2014). "Furthermore, in order to elucidate the mechanisms involved in the actions of the oil mixture, we also analyzed novel factors that may play a key role in the development of sarcopenia such as the HDAC-4-myogenin axis." (PMID 33375628, 2020). "HDAC4 may have a central role in sarcopenia, increasing muscle senescence and local inflammation." (PMID 33375628, 2020).
autism (4 papers, 2017 to 2025). Persistent deficits in social interaction and communication and interaction as well as a markedly restricted repertoire of activity and interest as well as repetitive patterns of behavior. "Dosage of HDAC4 has been implicated in ASD, with observed overexpression in the post-mortem brain tissue of individuals with ASD; conversely, deletions of the HDAC4 loci have been reported in individuals with syndromic autism." (PMID 28540026, 2017).
B-cell lymphoma (4 papers, 2015 to 2021). "Several studies have been focusing on unveiling the miR-155 oncogenic role in B-cell lymphomas, reporting that its targets NIAM, histone deacetylase 4 (HDAC4), and SHIP1." (PMID 34944752, 2021).
Duchenne muscular dystrophy (4 papers, 2022 to 2025). Duchenne muscular dystrophy (DMD) is a neuromuscular disease characterized by rapidly progressive muscle weakness and wasting due to degeneration of skeletal, smooth and cardiac muscle. "Previously, we have reported the crucial importance of HDAC4 in Duchenne Muscular Dystrophy, which is consistent with its protective role reported for another disease." (PMID 36613534, 2022).
gastric tumor (4 papers, 2019 to 2023). "HDAC4: The good aspect about HDAC4 is that all expression studies agreed that HDAC4 displays an increased expression in gastric tumors." (PMID 36358890, 2022). "Importantly, HDAC4 expression was found to be elevated in gastric tumors compared to healthy tissues, and in particular in specific molecular subgroups." (PMID 31703394, 2019). "Moreover, HDAC4 expression was elevated in gastric tumor samples compared to healthy tissue." (PMID 36982651, 2023). "For instance, MORC2 binds to carbonic anhydrase IX (CAIX) and recruits histone deacetylase 4 (HDAC4), which deacetylates of histone H3 at the promoter and represses the transcription of the CAIX gene; this gene plays a key role in gastric tumor cell growth and survival." (PMID 34839357, 2021).
leukemia (4 papers, 2015 to 2023). A malignant (clonal) hematologic disorder, involving hematopoietic stem cells and characterized by the presence of primitive or atypical myeloid or lymphoid cells in the bone marrow and the blood. "miR-155 expression in mice B cells causes pre-B cell proliferation and high-grade lymphoma or leukemia by repressing B cell lymphoma-6 (Bcl6) with different mechanisms, including HDAC4 repression." (PMID 36762207, 2023). "Taken together, these data support the idea that HDAC4 deficiency may promote disease progression in a subset of leukemia patients." (PMID 32726753, 2020). "Expression of miR-155 in mouse B cells causes proliferation of pre-B cells and high-grade lymphoma or leukemia by suppressing B cell lymphoma-6 (Bcl6) via various mechanisms, including HDAC4 downregulation." (PMID 36762207, 2023). "Another tumor suppressive activity of HDAC4, investigated in leukemia cells from AML patients but also observed in various cancer cell lines, provides a link with metabolism." (PMID 36762207, 2023).
liver fibrosis (4 papers, 2017 to 2024). "Meanwhile, hypermethylation of HDAC4 is associated with severe liver fibrosis in patients with hepatitis B-related chronic liver disease." (PMID 35602496, 2022). "The restoration of intracellular zinc concentrations and the modulation of ZIP14 expression by zinc orchestrated through MTF1 and HDAC4, appear to be essential determinants of the therapeutic response in hepatic fibrosis." (PMID 38221603, 2024). "A previous study has demonstrated the crucial impact of HDAC4 in regulating ECM deposition in a liver fibrosis model induced by CCL4." (PMID 38221603, 2024). "Therefore, this HDAC4-miR-206-MRTF-A axis may serve as a potential target for developing novel interventional strategies to prevent malicious liver fibrosis." (PMID 28548935, 2017). "Our results suggest that the ZnCl2 treatment ameliorates liver fibrosis by elevating intracellular zinc levels through MTF1-mediated regulation of ZIP14 expression and the reduction of ZIP14 deacetylation via HDAC4." (PMID 38221603, 2024). "Our data indicate that miR-206 is another downstream target of HDAC4 in the context of HSC activation and liver fibrosis and that miR-206 suppresses HSC activation likely through inhibiting MRTF-A expression." (PMID 28548935, 2017). "The present study highlights a novel mechanism whereby MRTF-A expression is regulated post-transcriptionally, via HDAC4-mediated repression of miR-206, during HSC activation and liver fibrosis in response to pro-fibrogenic stimuli." (PMID 28548935, 2017). "Also, zinc shows epigenetic modulatory role by interacting with HDAC4 and influencing the activity of HDAC4 on ZIP14 promoter during liver fibrosis." (PMID 38221603, 2024). "Therefore, our data reveal an HDAC4-miR-206-MRTF-A axis that can play a potentially important role in HSC activation and liver fibrosis." (PMID 28548935, 2017). "HDAC4 expression was up-regulated in HSC-T6 cells following TGF-β or PDGF stimulation and in the livers of mice induced to develop hepatic fibrosis by receiving CCl4 injection, TAA injection, or undergoing BDL, suggesting that HDAC4 levels may potentially serve as a marker for liver fibrogenesis." (PMID 28548935, 2017).
neurogenic muscle atrophy (4 papers, 2018 to 2025). "In this study, we showed that HDAC4 overexpression induces skeletal muscle atrophy, leading to a loss in soleus mass, whole muscle CSA, and fiber CSA." (PMID 40183248, 2025). "Overexpression of miR-206 decreased endogenous HDAC4 levels in the tibialis anterior muscles of mice, and miR-206 can attenuate denervation-induced rat skeletal muscle atrophy through the HDAC4-related signaling." (PMID 33246401, 2020). "Considering its crucial role, HDAC4 has been proposed as a potential therapeutic target for diseases characterized by neurogenic muscle atrophy, such as ALS or SMA, or for sarcopenia." (PMID 29477142, 2018).
pancreatic adenocarcinoma (4 papers, 2015 to 2024). "High HDAC-4 expression was also more frequently observed in pancreatic adenocarcinoma patients presenting earlier histopathological stage, at a non significant level though (p = 0.2818)." (PMID 26502922, 2015). "A similar negative association between HDAC-4 expression and the presence of distant metastasis has also been reported in human pancreatic adenocarcinomas." (PMID 38790909, 2024). "In clinical studies, elevated HDAC4 expression was significantly associated with the absence of organ metastases and tumor proliferative capacity in pancreatic adenocarcinoma." (PMID 37149664, 2023). "High HDAC-4 expression was noted in 34 (48.6 %) out of 70 pancreatic adenocarcinoma cases." (PMID 26502922, 2015). "On the contrary, high HDAC-4 expression has been correlated with the absence of organ and lymph node metastases in pancreatic adenocarcinoma." (PMID 33799478, 2021). "High HDAC-4 expression was more frequently observed in pancreatic adenocarcinoma patients with absence of lymph node metastases and increased tumor proliferative capacity, at a non significant level though (p = 0.0571 and p = 0.0576, respectively)." (PMID 26502922, 2015).
schizophrenia (4 papers, 2016 to 2022). A major psychotic disorder characterized by abnormalities in the perception or expression of reality. "First, one SNP (rs1063639) in the HDAC4 gene associates with the development of schizophrenia in a Korea population." (PMID 27847464, 2016). "Moreover, in patients with schizophrenia, HDAC4 mRNA is negatively associated with the expression of GAD67, a candidate gene of schizophrenia." (PMID 27847464, 2016). "A couple of evidence suggests that HDAC4 might be associated with the pathology of schizophrenia." (PMID 27847464, 2016). "In addition to novel GWS loci, we have identified a significant genetic correlation with schizophrenia and association of ASD with several neurodevelopmental-related genes such as EXT1, ASTN2, MACROD2, and HDAC4." (PMID 28540026, 2017). "However, the exact role of HDAC4 in the cognitive deficits of schizophrenia needs to be further investigated." (PMID 27847464, 2016). "Based on the present data, we speculate the disruption of gene function caused by DNVs and/or DNA methylation difference in COS could affect the expression of functional genes, such as HDAC4, related to the etiology of neuropsychiatric disorders, especially schizophrenia." (PMID 35783128, 2022). "Some evidence suggests that HDAC4 may be related to the pathology of schizophrenia." (PMID 35783128, 2022).
spinal muscular atrophy (4 papers, 2015 to 2025). A motor neuron disease that affect the muscles, and characterized by muscle weakness and atrophy resulting from progressive degeneration and irreversible loss of the anterior horn cells in the spinal cord (i.e., lower motor neurons) and the brain stem nuclei. "An increased level of HDAC4 has been found in SMA (spinal muscular atrophy) model mice and in SMA patient muscles." (PMID 25748626, 2015). "Similarly, an increased level of HDAC4 has been found in SMA (spinal muscular atrophy) model mice and in SMA patient muscles." (PMID 25748626, 2015). "Furthermore, high HDAC4 expression levels were detected in a mouse model of spinal muscular atrophy in ALS patients and in an ALS mouse model, suggesting that in the presence of neuromuscular defects, inactivation of HDAC4 may result in a suppression of muscle atrophy in a denervation model." (PMID 34074012, 2021).
Anxiety (3 papers, 2015 to 2024). Intense feelings of nervousness, tension, or panic often arise in response to interpersonal stresses. "Some evidence in the literature suggests that a reduction in HDAC4 levels may have a specific effect on the anxiety-like phenotype; in particular, downregulation of HDAC4 expression has been shown to prevent the development of the anxiety-like phenotype in stressed mice." (PMID 38785785, 2024). "Animals showed anxiety-like behavior and this behavior as well as the AChE chromatine structure and the entire HDAC enrichment profile were reversed by NaBu, an HDAC inhibitor; the restoration of mE1c expression level was however due to HDAC4 inhibition entirely." (PMID 26300730, 2015). "However, when Hdac4 was absent in forebrain excitatory neurons in another conditional knockout mouse model, CamKII-Cre/Hdac4, the mice were hyperactive, with deficits in memory and motor coordination, and reduced anxiety-like behaviors." (PMID 33488679, 2020).
brachydactyly type E (3 papers, 2022 to 2024). Brachydactyly type E (BDE) is a congenital malformation of the digits characterized by variable shortening of the metacarpals with more or less normal length phalanges, although the terminal phalanges are often short. "The HDAC4 gene has been proposed as being mainly responsible in producing the phenotypic aspects of the 2q37 microdeletion, especially brachydactyly type E, behavioral disorders, and ID—the marker clinical features in this syndrome." (PMID 36833393, 2023).
coronary artery disease (3 papers, 2021 to 2025). "Overexpression of miRNA-20a-5p also alleviates oxidizedlow-density lipoprotein (oxLDL)-induced inflammation and injury by targetinghistone deacetylase 4 (HDAC4) in human coronary artery endothelial cells, showingpromise in coronary artery disease (CAD) progression prevention." (PMID 40475735, 2025).
liver cancer (3 papers, 2019 to 2024). An epithelial or non-epithelial malignant neoplasm that arises from the liver. "The risk score calculated by the expression value of HDAC1, HDAC2, HDAC4, HDAC11, HAT1, and SIRT6 was an independent risk factor for liver cancer." (PMID 36124029, 2022). "Among them, HDAC7, HDAC4, SIRT7, KAT2A, and HDAC11 were the top five most upregulated genes, indicating that the expression of deacetylation-related genes played a dominant role in liver cancer compared with acetylation-related genes." (PMID 36124029, 2022).
medulloblastoma (3 papers, 2011 to 2022). A malignant, invasive embryonal neoplasm arising from the cerebellum. "We found that curcumin was effective in the Smo/Smo medulloblastoma model, which increased survival, while HDAC4 expression was reduced at the same time." (PMID 21501498, 2011). "Molecular analysis of curcumin-treated and control tumors revealed reduced HDAC4 expression and increased tubulin acetylation, suggesting that curcumin induces apoptosis by similar mechanisms in culture and in vivo medulloblastoma." (PMID 21501498, 2011). "Consistent with increased tubulin acetylation, curcumin inhibited HDAC activity and repressed HDAC4 expression in medulloblastoma cells." (PMID 21501498, 2011). "In this study, we demonstrate that curcumin induces apoptosis in medulloblastoma cells and is accompanied by reduced HDAC4 expression, increased tubulin acetylation, and arrest at the G2/M phase of the cell cycle followed by mitotic catastrophe, and cell death." (PMID 21501498, 2011). "We show that curcumin targets HDAC4 in medulloblastoma cells and reduces HDAC activity." (PMID 21501498, 2011). "However, given the cell-type specific expression pattern of HDAC4 we cannot exclude that such a link might exist in medulloblastoma cells." (PMID 21501498, 2011). "While curcumin treatment dramatically reduced HDAC4 phosphorylation in all three medulloblastoma cell lines, the subcellular localization of HDAC4 did not change after six hours of curcumin treatment." (PMID 21501498, 2011).